CD38 (CD38 molecule)
Diseases named in the same sentence as CD38 in open-access papers (continued):
Sharing a sentence is not in itself a finding about the gene and the disease.
tumor (continued). "We revealed the unique characteristics of CD38-negative CTCL cells, shedding light on how this phenomenon affected tumor progression after treatment." (PMID 40057636, 2025). "Immunohistochemically, the tumor cells were positive for ki-67, bcl-2, CD10, bcl-6, and CD38, but negative for bcl-2 and MUM-1." (PMID 39993110, 2025). "IHC confirmed the diagnosis of DLBCL (germinal center B-cell subtype), as the tumor cells were positive for Oct-2, CD20, PAX5, BCL-6, and CD10 and negative for CD38, CD138, MUM1, and CD30." (PMID 40432631, 2025). "This resulted in increased immune regulator molecules such as CTLA4, PDL1, Tim3, VISTA, LAG3, CD38, CD80, CD86, MHC Class II, and PD-L1 being presented on the surface of trogocytic tumor cells compared to non-trogocytic tumor cells." (PMID 40440354, 2025). "Immunohistochemistry confirmed DLBCL (germinal center B-cell subtype), with tumor cells positive for Oct-2, CD20, PAX5, BCL-6, and CD10 and negative for CD38, CD138, and MUM1." (PMID 40432631, 2025). "Although co-inhibition of CD38 and PD-L1 improves antitumor immune response in NSCLC as previously reported, the co-inhibition did not demonstrate anti-tumor effects in a SCLC mouse model in this study." (PMID 38533509, 2024). "Further differentiated plasma cells are usually located within the tumor stroma and are negative for CD20 and Ki67 but express, in addition to MUM1 and CD38, the characteristic molecule CD138." (PMID 38629072, 2024). "We identified that total CD8+, HLA-DR+CD38+ and Ki67+ of CD8+ T cells expression was not correlated with the percent change in tumor size." (PMID 39149474, 2024). "In the absence of tumor cells, ISB 2001 exhibited only minor T cell activation (as measured by CD25 upregulation on CD8+ and CD4+ T cells) compared to the CD3 × CD38 TCE control." (PMID 39261676, 2024). "Despite the broad expression of CD38 across human tissues, ISB 2001 demonstrated a reduced T cell activation profile in the absence of tumor cells when compared to TCEs targeting CD38 only." (PMID 39261676, 2024). "All these results indicated the robust anti‐tumor activity of CD38‐CAR‐T cells against MM cells, even though CD38 was not expressed on transduced CAR‐T cells." (PMID 37039305, 2023). "Not surprisingly, CD38 and CXCL13 were both highly correlated with T cells and other effector cells with tumor-killing abilities, which was consistent with their better prognosis." (PMID 35711935, 2022). "Tumor cells in NKCL were consistently negative for CD3, CD4, and CD5 and showed moderate CD2, CD38, CD56, and CD94 and heterogeneous expressions of CD7, CD8, CD16, and CD26." (PMID 35299754, 2022). "Baseline tumor tissue from patients with EOC (pre-treatment screening biopsies) and GBM (archival) had low infiltration by immune cells, generally not expressing CD38 and PD-L1." (PMID 35987165, 2022). "Anti-CD38 was used for auxiliary targeting and enhancing binding to anti-BCMA, rather than killing tumor cells directly." (PMID 34980210, 2022). "One patient (case 7) had a plasmablastic neoplasm expressing MUM1, CD38 and HHV8 but lacking CD20 and CD138, most consistent with an HHV8+ large B-cell lymphoma with plasmablastic features." (PMID 36013165, 2022). "Although subgroup analyses were limited by small sample sizes, clinical responses were not significantly influenced by baseline tumor BCMA and CD38 levels, MM cells in bone marrow, serum M protein or dose of infused CAR-Ts." (PMID 34627333, 2021). "Although CD38 plays an important role in converting nicotinamide adenine dinucleotide (NAD+) to adenosine, adenosine receptor antagonists did not suppress LLC1 tumor growth in our model." (PMID 34771674, 2021). "Tumor-infiltrating CD38− CD8+ T cells had a stronger IFN-γ secretion capacity than that in peripheral blood, but not CD38+ CD8+ T cells." (PMID 33934206, 2021). "Tumor cells are usually negative for CD45 and the pan-B-cell markers CD19 and CD20, and positive for CD38, CD79a, and CD138." (PMID 34930458, 2021).
tumor (continued). "Despite the fact that CD38-hcAbs effectively induced ADCC but not CDC in vitro, all three hcAbs reduced tumor growth in vivo at least as effectively as daratumumab." (PMID 32194826, 2020). "The results confirm that NK cells expressing the CD38-specific Nb36-CAR, but not those expressing the control Nb14-CAR, indeed effectively lyse CD38-expressing tumor cells." (PMID 32013131, 2020). "The BL tumor cells were generally negative for LMO2, but were strongly and diffusely cell membrane positive for CD38, and ≥ 80% of tumor cells were strongly nuclear positive for c-Myc." (PMID 31484540, 2019). "By contrast, the level of cADPR, another Ca2+ signaling second messenger produced by CD38, was not affected by stimulation with the PME of tumor cells." (PMID 25879940, 2015). "Immunohistochemical (IHC) staining of tumor cells expressed positivity for mature B cell markers CD20, CD19, CD10, CD23, CD45, and CD38 but negative for CD5,11c." (PMID 26380128, 2015). "RC cells had the following immunophenotype: positive for CD10, CD19, CD20, CD22, CD38, CD43, CD44, and CD79b and negative for CD3, CD4, CD5, CD8, CD11c, CD14, CD30, CD56, and CD200, which was identical to the primary tumor cells." (PMID 26515759, 2015). "The tumor showed the proliferation of large lymphoid cells with centroblastic morphology, which were positive for CD138, CD38, CD56 and MUM-1, and negative for CD20, CD79a, BCL-6 and HHV8." (PMID 26543559, 2015). "Immunohistochemistry demonstrated that the tumor cells were positive for CD138, IgA and CD79α, but negative for CD3, CD38, CD20, CD10, Bcl-6, CD56 and cytokeratin." (PMID 25009592, 2014). "The immunohistochemistry staining showed that the tumor cells were diffusely positive for S-100, CD1a, langerin and CD68, but negative for CD3, CD5, CD20, CD21, CD30, CD38, CD56, CD79a, ALK, HMB-45, Melan-A, pan-cytokeratin and MPO." (PMID 23388086, 2013). "The medullary invasion by blasts (reflection of the tumor mass) of the total sample of CD34+, CD34+ CD38− patients and those not expressing CD34+ was respectively 79.4%, 81.25%, 83.3% and 74.8%." (PMID 23667721, 2013). "The tumor cells are almost always negative for CD20 and CD79a but are always positive for CD138 and CD38, consistent with a postgerminal center phenotype." (PMID 22474449, 2012). "The tumor cells were CD45+, CD30+, CD38+, HHV-8 LANA-1+; but were negative for CD3-, CD20-, CD19-, and CD79a- and EBV RNA+ on in situ hybridization." (PMID 21320326, 2011). "Because immunostaining of tumor cells for CD20 was not characteristic of DLBCL, histopathology was re-examined, and IHC analysis revealed that the tumor cells were strongly positive for CD38 and CD138." (PMID 40160869, 2025). "Since recurrences are usually associated with down-regulation of tumor antigen after targeted therapies or incomplete elimination of residual tumor cells, selection of a target antigen that is not down-regulated (such as CS1 and CD38) is an attractive strategy." (PMID 37209218, 2023). "Interestingly, irradiated tumor cells upregulated their expression of CD73 and CD38 but not CD39, suggesting utilization of the non-canonical pathway of eADO generation." (PMID 37240219, 2023). "Therefore, despite the dramatic and promising clinical efficacy and safety of anti-CD38 and anti-BCMA agents, we still do not exactly know how neoplastic cells can escape from drug-induced tumor killing." (PMID 36614086, 2022). "CD38 CAR-T cells secreted large amounts of TNF-α, IFN-γ, IL-2 and granzyme when incubated with CD38-positive tumor cells compared with pan-T cells, and there was no significant change in the killing effect of CD38 CAR-T cells on tumor cells that did not express CD38." (PMID 34513682, 2021). "Daratumumab does not bind to mouse CD38, and therefore in these in vivo experiments, an anti-mouse CD38 antibody (anti-mCD38) was used that exhibited characteristics of daratumumab, i.e., mediated in vitro ADCC and ADCP of mouse CD38-expressing tumor cells." (PMID 33321969, 2020).
tumor (continued). "Immunophenotypically, the tumor cells are typically negative for common B-cell markers, T-cell markers, and CD30; however, they express markers of terminally differentiated B cells/plasma cells such as CD38, CD138, and MUM-1/IRF4." (PMID 29992063, 2018). "A routine immunohistochemistry antibody panel revealed that the tumor cells were negative for B-cell and T-cell markers (i.e., CD3, CD19, CD20, CD38, CD45RO, CD79a, CD138, and Pax-5), but were positive for CD30 and MUM-1, not defining the lineage of tumor cells." (PMID 28143608, 2017). "The tumor cells were observed to be negative for CD138 and CD38." (PMID 25013515, 2014). "In addition, assessment of the on-target/off-tumor activity of ISB 2001, which could contribute to CRS, showed a profile more similar to BCMA-targeted TCEs rather than a CD38-targeted TCE." (PMID 39261676, 2024).
infection (273 papers, 2004 to 2026). The state of being infected such as from the introduction of a foreign agent such as serum, vaccine, antigenic substance or organism. "WT and CD38-deficient (Cd38–/–) mice were infected with Mtb and the total lung bacterial burden was measured at 6 and 10 weeks post-infection." (PMID 40489538, 2025). "Based on our risk score, patients at high risk of early, severe infections and death can be easily identified upfront, when evaluated for the latest quadruplet induction therapies including an anti-CD38 mAb." (PMID 38062124, 2024). "Accordingly, patients receiving anti-CD38-based therapy have an increased risk of developing infections compared to patients treated with other backbone MM regimens." (PMID 39335161, 2024). "Expression of CD38 on the surface of numerous immune cells indicates its roles in pathogenic infection." (PMID 34485381, 2021). "This is evident in patients undergoing anti-CD38 antibody mediated immunotherapy, where increases in opportunistic pathogenic infection in such patients have been reported." (PMID 34485381, 2021). "Lessons learned from anti-CD38 antibody therapy suggest that depletion of subpopulations of immune cells expressing CD38 increase the susceptibility to infection." (PMID 31963337, 2020). "In contrast to causal attribution of CD38 in hematological malignancies many intriguing pieces of evidence suggest that CD38 is an essential component that serves to combat various infections by triggering innate immune response." (PMID 32709019, 2020). "In the present study, we demonstrated that CD38−/− mice experienced a significant weight loss and a more severe kidney injury two hours after LPS (20 mg/kg BW) infection compared to WT mice." (PMID 30915370, 2019). "Accordingly, CD38-deficient mice have increased susceptibility to infection as a consequence of reduced chemotactic activity and antigen presentation, modulation of bacterial uptake, and deficient T cell-dependent antibody and Th1 responses." (PMID 30042766, 2018). "Intriguingly, we noted that the strongest correlation to reduced %CD4+ T cells in HIV-2 aviremic infection was linked more to accumulation of PD-1+ and less to CD38+HLA-DR+ cells." (PMID 27525551, 2016). "Monitoring of the induction of CD8+CD38 high T cells upon pathogenic infection and their functionality in the future should deliver more in depth knowledge on the origin and suppressive potential of these cells." (PMID 23028866, 2012). "Authors also maintained that patient age, disease stage, CD38 expression, and IgVH mutation status had a significant impact on infection-related mortality." (PMID 22606052, 2012). "In a resting state, a higher percentage of APN-deficient AMs were CD38+ and lower percentage were Egr2+ when compared to WT, while after 10 hours of infection with A. fumigatus, percentages of both CD38+Egr2- and CD38+Egr2+ cells increased, with no change in CD38-Egr2+ cells." (PMID 40096083, 2025). "Patients treated with anti-CD38-based therapy are at increased risk of severe infections." (PMID 40786241, 2025). "Furthermore, scATAC-seq analysis of naïve lungs demonstrated that CD38+ TR-AMs possessed a distinct chromatin signature prior to infection, indicative of epigenetic priming and predisposition to a pro-inflammatory response." (PMID 39070650, 2024). "In particular, MM patients receiving anti-CD38 remain at risk for infection." (PMID 38793769, 2024). "CD38+ TR-AMs, are already present in naïve lungs, exhibit chromatin landscapes predisposed for a pro-inflammatory response, indicating epigenetic priming as a key factor in their infection response." (PMID 39070650, 2024). "The expression level of CD38 on T cells may also be related to infection by pathogenic microorganisms such as viruses." (PMID 39588376, 2024).
infection (continued). "CD38 is robustly induced during infection and the ensuing inflammation, although whether CD38 has pathogenic or regulatory effects varies depending on the diseases, immune cells, or animal models analyzed." (PMID 36998049, 2023). "Both in vivo and in vitro models have been used in combination with CD38 deficiency, ligating/blocking antibodies or agonists/antagonists of CD38 activities in order to decipher the effects of CD38 in different cell types and infection settings." (PMID 31963337, 2020). "Therefore, CD38 has been clearly linked to inflammation and has been the subject of considerable study, particularly in the context of infection." (PMID 33329591, 2020). "Furthermore, a more sophisticated understanding of the structure and function of CD38 has led to identification of therapeutic targets and potential treatments for conditions associated with metabolic dysfunction in infection, aging, and cancer." (PMID 31214171, 2019). "While the ability of NK cells to secrete IFN-γ in response to HIV-infected cells was associated with decreased risk of infection, generalized NK cell activation (as measured primarily by expression of CD38 and/or HLA-DR) was associated with increased risk of HIV acquisition." (PMID 26973646, 2016). "In our study, the CD38+ CD4+ T cells circulating during infection displayed a phenotype associated with recent activation and cytotoxic potential, suggesting that this cell population may be a subset of cytolytic CD4+ T cells." (PMID 27662621, 2016). "We aimed to determine whether the increase in CD38 in old murine macrophages after infection is directly associated with enhanced inflammation induced by the oral pathogens Aggregatibacter actinomycetemcomitans (Aa) or Porphyromonas gingivalis (Pg) when compared to young controls." (PMID 40649955, 2025). "Is it generally recommended that prophylactic antiviral therapy, antibacterial agents, and vaccination against infections be administered before initiating anti-CD38-based therapy?" (PMID 40786241, 2025). "Conversely, the effector CD4+ T‐cell population in IAV‐ and SFV + IAV–infected lungs displayed increased levels of both single‐positive and double‐positive CD38+ PD1+ phenotype cells compared with SFV infection at 7 and 10 dpi." (PMID 39971320, 2025). "These preventive strategies, combined with patient education on infection risk and prompt symptom recognition, are essential to minimize infection-related complications and support anti-CD38-based treatment adherence in RRMM." (PMID 40786241, 2025). "While the frequency of the CD38+CD19+ B cell population declined rapidly after the first day, the frequency of the CD38+CD4+ T cell population remained relatively stable throughout the first week post-infection." (PMID 40733503, 2025). "Infection elicits an inflammatory response and dysregulates genes associated with the innate immune system (CCL20, CD38, LCN2 and NR4A3)." (PMID 39666439, 2025). "Infected MDMs from CCR2ΔMHCII mice had significantly weaker CD38 staining compared to CCR2WT mice at 3 weeks post-infection, mirroring the defect in Cd38 transcription observed in MDM_2 cells from CCR2ΔMHCII mice." (PMID 40489538, 2025). "The complexity of CD38 is detailed in recent reviews, emphasizing its diverse and often poorly understood biological roles, such as in infection defense, chronic inflammation, and autoimmunity." (PMID 40444214, 2025). "Following infection and viral replication, the frequency of activated (CD38+HLA-DR+) CD4+ and CD8+ T cells increased rapidly, consistent with HIV-1-induced inflammation and the emergence of HIV-1-specific T cell responses." (PMID 41279654, 2025). "For example, a lower expression of the activation marker CD38 has been observed on early memory spike-specific CD8+ T cells after vaccination compared to natural infection, indicating enhanced activation after infection with different kinetics." (PMID 40029063, 2025).